MYD88 (MYD88 innate immune signal transduction adaptor)
Diseases named in the same sentence as MYD88 in open-access papers (continued):
Sharing a sentence is not in itself a finding about the gene and the disease.
MYD88 also shares sentences with these, for which no sentence is quoted: enteritis (7 papers); nonalcoholic steatohepatitis (7); acute liver failure (4); acute myocardial infarction (4); Crohn disease (4); hairy cell leukemia (4); acute sinusitis (3); colon adenocarcinoma (3); demyelinating disease (3); hematological cancers (3); Lewis lung carcinoma (3); staphylococcal infection (3); systemic inflammatory response syndrome (3); triple-negative breast carcinoma (3); vascular dementia (3); viral diseases (3); adult-onset Still disease (2); Anaplastic Thyroid Carcinoma (2); aortic atherosclerosis (2); apical periodontitis (2); chronic granulomatous disease (2); chronic kidney disease (2); colon (2); common variable immunodeficiency (2); dengue (2); Diarrhea (2); erectile dysfunction (2); H1N1 influenza (2); hepatitis B (2); herpes simplex encephalitis (2).
A further 135 diseases each share a sentence with MYD88 in 2 papers or fewer.